EMX2OS (EMX2 opposite strand/antisense RNA)
Diseases named in the same sentence as EMX2OS in open-access papers (continued):
Sharing a sentence is not in itself a finding about the gene and the disease.
cancer (10 papers, 2018 to 2025). A tumor composed of atypical neoplastic, often pleomorphic cells that invade other tissues. "EMX2OS was previously reported to be implicated in cellular processes correlated with disease development in various cancers." (PMID 37069939, 2023). "Based on the previous reports about the function of EMX2OS in other cancers, the association of EMX2OS with clinical conditions was estimated." (PMID 37069939, 2023). "The pan-cancer analysis revealed that EMX2OS was correlated with poor survival consequences in several cancer types." (PMID 36287118, 2022). "The results demonstrated that eRNA EMX2OS is correlated with the age, grade, stage, and cancer status." (PMID 34731149, 2021). "The correlation analysis demonstrated that eRNA EMX2OS is correlated with age, grade, stage, and cancer status." (PMID 34731149, 2021). "Pan-cancer analysis showed that significant expression and survival differences of EMX2OS existed in several types of cancers." (PMID 33234727, 2020). "In a variety of cancers, EMX2OS acts as an enhancer RNA and may affect cancer progression by regulating gene expression and cell signaling pathways." (PMID 40994527, 2025). "EMX2OS, as a lncRNA, has been reported to play an important role in many cancers." (PMID 34731149, 2021). "The function of EMX2OS in cancer differs depending on cell background." (PMID 34218270, 2021). "Such common chromosomal abnormalities and metabolic pathway disorders in cancer cell lines may lead to deviations in their response to ferroptosis and the regulation mode of EMX2OS from that of normal cells, making it impossible to fully simulate the physiological state of neonatal lung epithelium." (PMID 40994527, 2025). "To validate the results, we explored the differential expression and prognostic value of EMX2OS and its correlation with EMX2 in pan-cancer data (32 other cancer types) from The Cancer Genome Atlas (TCGA) as an internal validation." (PMID 33234727, 2020). "However, in our study, EMX2OS did not demonstrate differential expression levels in cancer cells versus ANCTs." (PMID 34703931, 2021).
EMX2OS also shares sentences with these, for which no sentence is quoted: cervical squamous cell carcinoma (2 papers); clear cell carcinoma of the kidney (2); endocervical adenocarcinoma (2); stomach adenocarcinoma (2); uveal melanoma (2); colon adenocarcinoma (1); glioblastoma (1); infection (1).